KCNE4 (potassium voltage-gated channel subfamily E regulatory subunit 4)
Description:
Ancillary protein that functions as a regulatory subunit of the voltage-gated potassium (Kv) channel complex composed of pore-forming and potassium-conducting alpha subunits and of regulatory beta subunits. KCNE4 beta subunit modulates the gating kinetics and enhances stability of the channel complex. Associates with KCNQ1/KVLTQ1 alpha subunit to inhibit potassium currents. [Isoform 2]: May inhibit KCNQ4-mediated potassium currents.
Synonyms: MiRP3
Tractability: Antibody: UniProt predicts a signal peptide or a membrane-spanning region.
Gene: Protein-coding gene on chromosome 2 (223,052,190 to 223,198,399, forward strand). Ensembl gene ENSG00000152049.
Subcellular location: Membrane
Subcellular location (Human Protein Atlas): Microtubules; Nuclear bodies
Pathways (Reactome):
Muscle contraction: Phase 2 - plateau phase; Phase 3 - rapid repolarisation
Gene Ontology:
Molecular function: protein binding; transmembrane transporter binding; delayed rectifier potassium channel activity; potassium channel regulator activity; voltage-gated potassium channel activity involved in ventricular cardiac muscle cell action potential repolarization; voltage-gated potassium channel activity
Biological process: membrane repolarization during action potential; potassium ion export across plasma membrane; regulation of heart rate by cardiac conduction; regulation of ventricular cardiac muscle cell membrane repolarization; ventricular cardiac muscle cell action potential; membrane repolarization during ventricular cardiac muscle cell action potential; monoatomic ion transport
Cellular component: voltage-gated potassium channel complex; membrane
Genetic constraint (gnomAD): Loss-of-function variants: 6 observed, 9.65 expected, observed/expected ratio (o/e) 0.62, 90% interval 0.34 to 1.23. That is too few expected variants to judge how well the gene tolerates losing a copy. Missense variants: 222 observed, 241.64 expected, observed/expected ratio (o/e) 0.92, 90% interval 0.82 to 1.03. Synonymous variants: 115 observed, 109.15 expected, observed/expected ratio (o/e) 1.05, 90% interval 0.9 to 1.23.
Homologues: Orthologues: chimpanzee KCNE4 (99% identical), macaque KCNE4 (98% identical), rabbit KCNE4 (94% identical), rat Kcne4 (91% identical), mouse Kcne4 (90% identical), pig KCNE4 (90% identical), guinea pig KCNE4 (88% identical), tropical clawed frog KCNE4 (47% identical), zebrafish kcne4 (39% identical), dog KCNE4 (36% identical).
Diseases named in the same sentence as KCNE4 in open-access papers:
KCNE4 is named in the same sentence as 21 diseases in open-access papers, as found by Europe PMC text mining. Sharing a sentence is not in itself a finding about the gene and the disease. The quoted sentences say what the papers report.
Arrhythmia (3 papers, 2011 to 2022). Any cardiac rhythm other than the normal sinus rhythm. "We next quantified the effects of Kcne4 deletion on arrhythmia predisposition in the context of an ischemic substrate (IR injury by coronary artery ligation), mimicking the conditions thought to be required for SCD." (PMID 29844497, 2018). "KCNE4, a cardiac arrhythmia-associated potassium channel β-subunit, is upregulated by 5α-dihydrotestosterone (DHT)." (PMID 29844497, 2018). "Here, we again found similar QTc prolongation in aging male and female Kcne4−/− mice, but unexpectedly discovered that despite this, aging males were still more predisposed than aging females to Kcne4-linked arrhythmias, when challenged with an imposed IR injury." (PMID 29844497, 2018). "The baseline induction of cardioprotective pathways in female Kcne4−/− mice was one plausible explanation for their tolerance to IR injury, but were there additional mechanisms underlying the increased IR injury-induced arrhythmia predisposition in Kcne4−/− males versus females?" (PMID 29844497, 2018). "We next tested whether enhanced RISK/SAFE pathway induction was causally linked to the reduced IR susceptibility in female versus male Kcne4−/− mice, by quantifying the effects on post-IR arrhythmia incidence of pharmacological inhibitors of ERK1/2 (U0126), AKT (wortmannin) and STAT3 (Ag490)." (PMID 29844497, 2018). "The finding of very rare genetic variants with likely functional significance, i.e. p.M1T in KCNE3 and p.E141A in KCNE4, in controls is interesting and suggests that such variants may contribute to the arrhythmia risk in various conditions in the general population." (PMID 21967835, 2011). "Here we show that potassium voltage-gated channel subfamily E regulatory subunits 3 and 4 (KCNE3, KCNE4) are uniquely upregulated at arrhythmia sites within scarred myocardium." (PMID 35149693, 2022). "In female mice, Kcne4 deletion was not as effective at increasing reperfusion arrhythmia incidence (P = 0.31)." (PMID 29844497, 2018).
autoimmune disease (3 papers, 2021 to 2024). A disorder resulting from loss of function or tissue destruction of an organ or multiple organs, arising from humoral or cellular immune responses of the individual to their own tissue constituents. "Our results situate the regulatory subunit KCNE4 as a target for therapeutic approaches at the onset of autoimmune diseases, which are characterized by aberrant activity of Kv1.3 in leukocytes." (PMID 34272451, 2021). "In leukocytes, KCNE4 has an important role in regulating KCNA3 (Kv1.3) to act as an inhibitor of cell proliferation, activation, apo-regulation, autoimmune diseases, and T cell proliferation and activation." (PMID 35915077, 2022). "Therefore, it would be interesting to analyze the contribution of KCNE4 to SLE and other autoimmune diseases." (PMID 34272451, 2021).
glioblastoma (3 papers, 2016 to 2025). The most malignant astrocytic tumor (WHO grade IV). "KCNE4 is one of the genes that modify ion channels in glioblastoma." (PMID 39281062, 2022). "Glioblastoma studies included E5 (KCNJ10, KCNN3), E21 (KCNAB2), E26 (KCNE2, KCNJ13), E27 (KCNE4, KCNMB2-AS1), E31 (KCNJ10), E50 (KCND3), and E51 (KCNIP1, KCNJ16, KCNN2)." (PMID 40867621, 2025). "Within the shadowed columns, glioblastoma appears to have the highest number of modified ion-channel genes (namely: FXYD5, KCNE3, KCNE4, CLIC1, TRPM3)." (PMID 27716384, 2016). "Within the potassium intermediate/small conductance calcium-activated channels, expression of 3 genes (namely KCNE3, KCNE4, KCNN4) has been found altered in the current study, namely in glioblastoma and lung adenocarcinoma." (PMID 27716384, 2016).
anhidrosis (2 papers, 2025 to 2026). Lack of sweating or the ability to sweat when provoked by the appropriate stimulus. "Although the genetics of anhidrosis in horses is relatively unstudied, one recent publication attributed risk of equine anhidrosis to a missense variant in KCNE4." (PMID 39953936, 2025). "A prior study has suggested that equine anhidrosis is associated with a missense variant (rs68643109) in the Potassium Voltage‐Gated Channel Subfamily E Regulatory Subunit 4 (KCNE4) gene." (PMID 39953936, 2025). "Given this, we aimed to test the validity of the claim that anhidrosis results from the missense variant in KCNE4 (rs68643109) utilizing a quantitative intradermal terbutaline sweat test (QITST), which is the gold standard in clinical practice for the evaluation of equine anhidrosis." (PMID 39953936, 2025). "Since all 50 horses tested in our population produced sweat regardless of genotype, and the previously associated allele is present at a high frequency across datasets, these data fail to validate the missense variant within the KCNE4 gene as causative of or contributing to equine anhidrosis." (PMID 39953936, 2025). "A missense variant in KCNE4 (NC_009149.3:g.11813731A>G) was proposed as a risk allele, although its association with anhidrosis was not reported." (PMID 42035749, 2026). "Collectively, these data do not support a role of the KCNE4 variant or the GWA SNV in equine anhidrosis." (PMID 42035749, 2026).
glioma (2 papers, 2021 to 2022). A benign or malignant brain and spinal cord tumor that arises from glial cells (astrocytes, oligodendrocytes, ependymal cells). "Through TCGA database, we identified that the eight key genes (PCDH18, PPL, DEPP1, VASN, KCNE4, MYBPH, C5AR2, and MARCH4) were associated with the survival of patients with glioma." (PMID 39281062, 2022). "Overexpression of PCDH18, PPL, DEPP1, VASN, KCNE4, MYBPH, and C5AR2 in glioma and low expression of MARCH4 were associated with poor survival." (PMID 39281062, 2022). "Overexpression of PCDH18, PPL, DEPP1, VASN, KCNE4, MYBPH, and C5AR2 genes or low expression of MARCH4 gene in glioma patients was associated with poor survival." (PMID 39281062, 2022). "KCNE4 expression was characterized by a 2.9-fold increase in glioma compared to the healthy tissues." (PMID 33419226, 2021). "Of the 508 patients with glioma, the expression of PCDH18 (p < 0.001), DEPP1 (p < 0.001), VASN (p < 0.001), KCNE4 (p < 0.01), MYBPH (p < 0.001) and MARCH4 (p < 0.01) genes was significantly different between G2 and G3." (PMID 39281062, 2022).
acute lymphoblastic leukemia (1 paper, 2026). Leukemia with an acute onset, characterized by the presence of lymphoblasts in the bone marrow and the peripheral blood. "A negatively charged 145D/E polymorphic variant of KCNE4 has been associated with immune system disorders, such as allergic rhinitis and childhood acute lymphoblastic leukemia." (PMID 42159582, 2026).
bladder cancer (1 paper, 2019). "KCNE4, an ion channel gene, was found to show abnormal expression level in bladder cancer samples." (PMID 31212967, 2019).
heart failure (1 paper, 2017). Inability of the heart to pump blood at an adequate rate to meet tissue metabolic requirements. "Although KCNE4 expression dropped ~40% in human heart failure, it was still the predominant KCNE subunit." (PMID 28228734, 2017).
melanoma (1 paper, 2022). A malignant, usually aggressive tumor composed of atypical, neoplastic melanocytes. "We demonstrated that KCNE4 expression is also present in podoplanin-positive cells in human melanoma metastatic LNs." (PMID 35915077, 2022). "The roles of KCNE4 in chemokine production and cell adhesion were examined using primary lymphatic endothelial cells, and demonstrated that Ccl17 and Ccl19, which are involved in melanoma metastasis, were upregulated by KCNE4, as well as Mmp3 matrix metalloproteinase." (PMID 35915077, 2022). "Immunostaining was performed to determine whether KCNE4, which was upregulated in the mouse melanoma metastasis model, was also expressed in human lymph node tissues to which melanoma had metastasized." (PMID 35915077, 2022). "Although it is unclear how melanoma induces KCNE4 in lymphatic vessel endothelium, KCNE4 co-localized with KCNQ1 in LNs, suggesting that KCNE4 regulates KCNQ1 in lymphatic endothelium." (PMID 35915077, 2022).
metastatic melanoma (1 paper, 2022). A melanoma that has spread from its primary site to another anatomic site. "In conclusion, we found that LN metastatic melanoma induces KCNE4 expression in the endothelium of LNs." (PMID 35915077, 2022). "Expression of KCNE4 was detected in human LNs with metastatic melanoma." (PMID 35915077, 2022).
Ventricular arrhythmia (1 paper, 2018). "Strikingly, castration also completely ablated Kcne4 deletion-dependent susceptibility of male mice to IR-induced ventricular arrhythmias." (PMID 29844497, 2018). "One limitation of our study is that, perhaps surprisingly, human KCNE4 gene variants have not yet been linked to ventricular arrhythmias, although a KCNE4 polymorphism (E145D, short isoform numbering) is associated with increased risk of AF47." (PMID 29844497, 2018). "In contrast, Kcne4 deletion in age-matched males does not precondition; it impairs post-ischemic RISK/SAFE pathway induction; and it predisposes to IR injury-induced ventricular arrhythmias." (PMID 29844497, 2018).
cancer (5 papers, 2016 to 2024). A tumor composed of atypical neoplastic, often pleomorphic cells that invade other tissues. "Our study showed that KCNE4 is closely associated with the prognosis of cancer patients." (PMID 39281062, 2022). "Despite the importance of ion channel regulation in tumorigenesis, the role of KCNE4 in cancer remains poorly understood." (PMID 38462626, 2024). "To analyze the changes that occur in LNs before cancer cell metastasis, we analyzed the gene expression changes of SLNs in the early stages of metastasis in our model and found that Kcne4 and Slc7a11 were increased." (PMID 35915077, 2022). "We analyzed the gene expression changes in SLNs and found that Kcne4 and Slc7a11 were induced in lymphatic endothelium in the early stages of metastasis before cancer cells had metastasized." (PMID 35915077, 2022). "Moreover, KCNE4 may be a promising strategy for the development of novel anti-cancer therapeutics specifically directed against CAFs." (PMID 38462626, 2024). "Moreover, we had shown that KCNE4 could actively promote tumor-promoting phenotypes in CAFs, indicating its critical role in cancer progression." (PMID 38462626, 2024). "Other highly upregulated genes in mammospheres included the ion channel KCNE4 and the monoamine oxidase MOAB, which have not been associated with cancer stemness before." (PMID 34680485, 2021).
tumor (4 papers, 2022 to 2025). "Given this, it is plausible that elevated KCNE4 expression in CAFs represents an adaptation to the potassium-rich milieu of the tumor immune microenvironment." (PMID 38462626, 2024). "We subsequently utilized CRC single-cell sequencing data from the GEO database to confirm that KCNE4 is predominantly expressed in CAFs within tumor tissues and its expression is coincident with that of malignant CAFs markers." (PMID 38462626, 2024). "Our investigation into the expression of KCNE4 in CRC revealed a positive correlation with tumor stage, and T and N classification, suggesting a strong link between elevated KCNE4 levels and poor clinical prognosis." (PMID 38462626, 2024). "Expression analysis of primary cultured CAFs and tumor cell lines revealed a significantly higher expression of KCNE4 in CAFs than in tumor cells." (PMID 38462626, 2024). "Our results demonstrated that conditioned media from KCNE4-knockdown CAFs weakened the migration-promoting effects of CAFs on tumor cells." (PMID 38462626, 2024). "Our results indicated a significant upregulation of KCNE4 in tumor tissue compared to adjacent normal tissue, which were in line with TCGA-CRC paired analysis." (PMID 38462626, 2024). "In contrast, conditioned media from KCNE4-overexpressing NAFs enhanced the migration-promoting effects on tumor cells." (PMID 38462626, 2024). "Further investigation is needed to determine the relative importance of KCNE4 in tumor cells versus CAFs." (PMID 38462626, 2024). "CAFs in the control group exhibited stronger adhesion to tumor cells compared to those with KCNE4 knockdown." (PMID 38462626, 2024). "In each experimental group, liver slices were stained with hematoxylin-eosin (HE), revealing noticeable tumor metastatic foci in the liver in the NAFs overexpressing KCNE4." (PMID 38462626, 2024). "Here, we report for the first time that overexpression of KCNE4 in normal fibroblasts drives the conversion of NAFs to CAFs and enhances tumor cell metastasis." (PMID 38462626, 2024). "Notably, we found that KCNE4 expression was primarily detected in fibroblasts and significantly higher than that in tumor cells." (PMID 38462626, 2024). "Meanwhile, overexpression of KCNE4 in CAFs enhanced adhesion between CAFs and tumor cells." (PMID 38462626, 2024). "CCL17 is a ligand for CCR4, which activates CCR4-expressing Th2 cells and regulatory T-cells (Tregs) and suppresses effector cells; KCNE4 may contribute to tumor cell survival through activation of Tregs via increasing CCL17 production." (PMID 35915077, 2022). "We extracted proteins from both tumor and adjacent normal tissues from 12 CRC patients and quantified the expression level of KCNE4 using Western blotting." (PMID 38462626, 2024). "To further elucidate the role of KCNE4 in CAF and NAF cells, we isolated and cultured these cell types from both tumor and adjacent normal tissues of CRC patients." (PMID 38462626, 2024). "Hence, in order to determine the impact of elevated KCNE4 expression in NAFs on liver metastasis of CRC cells, we conducted rigorous in vivo assays by injecting NAFs and CRC tumor cells into the spleens of nude mice." (PMID 38462626, 2024). "Mechanistically, we noted that knockdown of KCNE4 in CAFs resulted in a downregulation of malignant CAF markers, a decrease in adhesion between CAFs and tumor cells, and a reduction in CAF-mediated pro-metastatic effects on tumor cells." (PMID 38462626, 2024). "Univariate independent prognostic analysis showed that age (p < 0.001), tumor grade (p < 0.001), PCDH18 (p < 0.05), PPL (p < 0.01), DEPP1 (p < 0.01), VASN (p < 0.001), KCNE4 (p < 0.001), MYBPH (p < 0.001), C5AR2 (p < 0.01), and MARCH4 (p < 0.01) gene expression levels were significantly different." (PMID 39281062, 2022).
KCNE4 also shares sentences with these, for which no sentence is quoted: allergic rhinitis (1 paper); cardiac arrhythmia (1); cardiac hypertrophy (1); colorectal cancer (1); immune system disorder (1); lung adenocarcinoma (1); multiple sclerosis (1); viral infection (1).